PLPPR2 (phospholipid phosphatase related 2)
Synonyms: PRG-4; LPPR2; PRG4
Tractability: Antibody: UniProt predicts a signal peptide or a membrane-spanning region; its Gene Ontology location is reachable by antibodies, with medium confidence. PROTAC: its protein half-life has been measured.
Gene: Protein-coding gene on chromosome 19 (11,355,386 to 11,365,698, forward strand). Ensembl gene ENSG00000105520.
Subcellular location: Membrane
Subcellular location (Human Protein Atlas): Nucleoplasm
Pathways (Reactome):
Signal Transduction: Lysosphingolipid and LPA receptors
Gene Ontology:
Molecular function: protein binding
Biological process: phospholipid dephosphorylation; phospholipid metabolic process; signal transduction
Cellular component: plasma membrane; membrane
Genetic constraint (gnomAD): Loss-of-function variants: 11 observed, 38.48 expected, observed/expected ratio (o/e) 0.29, 90% interval 0.18 to 0.47. The upper end of that interval is the gene's LOEUF score, 0.47, which puts it in group 2 of 6, group 1 being the genes least tolerant of losing a copy. Missense variants: 497 observed, 624.62 expected, observed/expected ratio (o/e) 0.8, 90% interval 0.74 to 0.86. Synonymous variants: 260 observed, 280.83 expected, observed/expected ratio (o/e) 0.93, 90% interval 0.84 to 1.03.
Homologues: Orthologues: chimpanzee PLPPR2 (99% identical), macaque PLPPR2 (99% identical), rat Plppr2 (97% identical), mouse Plppr2 (97% identical), dog PLPPR2 (85% identical), guinea pig PLPPR2 (82% identical), rabbit PLPPR2 (79% identical), pig PLPPR2 (70% identical), zebrafish plppr2a (45% identical), zebrafish plppr2b (41% identical), tropical clawed frog plppr2 (40% identical), Caenorhabditis elegans plpp-1.1 (15% identical), and 8 more. Paralogues in human: PLPPR1 (35% identical), PLPPR5 (34% identical), PLPPR3 (27% identical), PLPPR4 (27% identical), PLPP2 (16% identical), PLPP3 (15% identical), PLPP1 (15% identical), PLPP5 (12% identical), PLPP4 (11% identical).
Diseases named in the same sentence as PLPPR2 in open-access papers:
PLPPR2 is named in the same sentence as 3 diseases in open-access papers, as found by Europe PMC text mining. Sharing a sentence is not in itself a finding about the gene and the disease. The quoted sentences say what the papers report.
breast carcinoma (1 paper, 2022). "PLPPR2 has been associated with several cancers including colorectal, pancreatic and breast cancer cell lines and tissues." (PMID 36187351, 2022). "For example, PLPPR2 expression is deregulated in colorectal cancer patient samples and cells, while in breast cancer samples, PLPPR2 shows high frequency of an aa substitution at T278 (PLPPR2 T278S), potentially worsening breast cancer outcome." (PMID 36187351, 2022).
PLPPR2 also shares sentences with these, for which no sentence is quoted: colorectal cancer (1 paper); tumour (1).